RNU6-617P (RNA, U6 small nuclear 617, pseudogene)
Gene: Small nuclear RNA gene on chromosome 2 (131,602,790 to 131,602,896, forward strand). Ensembl gene ENSG00000251956.
Homologues: Orthologues: macaque U6 (93% identical), macaque U6 (92% identical), guinea pig U6 (77% identical), dog U6 (74% identical), pig U6 (65% identical). Paralogues in human: RNU6-473P (100% identical), RNU6-848P (100% identical), RNU6-1049P (99% identical), RNU6-127P (99% identical), RNU6-1239P (98% identical), RNU6-1268P (98% identical), RNU6-816P (98% identical), RNU6-1021P (93% identical), RNU6-286P (93% identical), RNU6-631P (93% identical), RNU6-749P (93% identical), U6 (93% identical), and 1286 more.